CD4 (CD4 molecule)
Diseases named in the same sentence as CD4 in open-access papers (continued):
Sharing a sentence is not in itself a finding about the gene and the disease.
infection (continued). "As it was, our current experimental design mimics the first phase of infection (primary infection) with a high concentration of CD4 T cells that are infected in a short period of time and the virus that replicates rapidly." (PMID 35163318, 2022). "CD4+ T cell depletion during long-term infection leads to persistent MHV68 replication in the lungs due to the rise in dysfunctional, suppressive CD8+ T cell population (40, –, 42)." (PMID 35968944, 2022). "Of the four patients with CD4 counts < 200 cells/mm3, three were treated for secondary infection, with 2 confirmed organisms." (PMID 35148782, 2022). "Functional T and B cells are essential to prevent reactivation in murine model, as depletion of CD4+ and CD8+ at the same time, as well as depletion of T cells in B cell-deficient mice resulted in infection persistence." (PMID 36266777, 2022). "Our studies suggest that non-permissive endometrial stromal fibroblasts (eSFs) from the FRT mucosa can markedly enhance infection: CD4+ T cells can be infected at up to 100-fold higher rates when co-cultured with eSFs." (PMID 36016345, 2022). "The Th2 cytokine IL-4 produced primarily by CD4+GATA4+ T cells is essential for expulsion of adult worms during primary infection." (PMID 35757733, 2022). "Depletion of ILC2s results in a failure to expel Nippostrongylus brasiliensis, and impairs IL-4-driven differentiation of Th2 CD4+ T cells following infection with Heligmosomoides bakeri." (PMID 36238293, 2022). "A study on patients hospitalized with pH1N1 infections also found that the CD4 and CD8 T cell responses were lower for those severe cases, compared with those with mild infections." (PMID 35858844, 2022). "As part of the cell-mediated immune response, infected CD4+ T cells underlie clearance by CD8+ cytotoxic T lymphocytes (CTLs), which are subsequently activated upon infection and mostly specific for the Gag proteins of HIV." (PMID 35202165, 2022). "CD4+ T cells were FACS sorted from FRTs 17 days post infection and processed for bulk RNA sequencing." (PMID 35196366, 2022). "Prior to infection, both the huNRG and huDRAG-A2 mice showed a similar abundance of human CD4+ T cell infiltration within the vaginal mucosa of both huNRG and huDRAG-A2 mice." (PMID 36146734, 2022). "NK cell activation following vaccination and infection can be modulated by antigen-specific CD4+ T cell IL-2 secretion." (PMID 35192547, 2022). "Based on these inputs, our model indicated an initial mixture of primarily CD4+ Tregs (51.3%), Th1 (3.2%), Th17 (2.3%), and Th22 (43.2%) cells prior to infection with C. difficile." (PMID 36418318, 2022). "It is possible that ECs contribute to infection of resting memory CD4+ T cells through transinfection and through direct effects on target cells following integrin engagement." (PMID 34465136, 2022). "HIV-1 and HTLV-1 initially infect mDCs as an intermediate and eventually spread infection to target CD4+ T cells." (PMID 36146843, 2022). "The elicitation of robust NS1 CD4 T cell reactivity further demonstrates the active infection of IBV within the B6 mice." (PMID 35215193, 2022). "Next, on Day 60 after LCMV Armstrong infection, when CD4 memory is well established, 1 × 105 SMARTA memory CD4+ T cells were purified and transferred into naïve mice, which were then challenged with B16-GP." (PMID 35784297, 2022). "Studies have confirmed that CD8+ T cells predominate in the early stages of the disease, with CD4+ T cells mediating the adaptive response at later times of post infection." (PMID 35215836, 2022). "This proposed function of PSGL-1 as a viral homing molecule would be especially relevant for HIV-1 pathogenicity during the early phases of infection, when the gut is still populated with a large reservoir of target CD4 + T cells." (PMID 35597982, 2022). "The results suggested that T lymphocytes were infected and in certain patient CD4 + T cells showed a high infection rate." (PMID 35277473, 2022).
infection (continued). "While LASV acute disease appears to be driven primarily by CD8 T cells, both CD4 and CD8 T cells are responsible for acute disease in ML29 infection; 100% survival is only seen with a double depletion of both CD4 and CD8 T cells." (PMID 36289695, 2022). "The frequency of circulating CD4+ T cells declined within the first 2 weeks of infection and remained depressed throughout the duration of SIV infection, but the trend was similar between groups (P = 0.5786)." (PMID 36712332, 2022). "Untreated, HIV reduces the number of CD4+ T cells in the body, making the person more likely to get other infections or HIV-related cancers." (PMID 36417469, 2022). "Other investigations have shown a function for the mannose receptor in astrocyte infection, whereas brain-tropic isolates have been found to need fewer CD4 on the cell surface for effective infection." (PMID 35677043, 2022). "In cats experimentally infected with B. henselae, the number of CD4+ T-lymphocytes decreased after infection, and interferon-γ and tumor necrosis factor-α were identified as important keys in eliminating B. henselae infection." (PMID 36425135, 2022). "The results showed an abundance of CD4+CD25+ and CD4+ transforming growth factor-beta (TGF-β)+ T regulatory cells in the feathers of MDV-infected chickens at 21 days post-infection." (PMID 35062316, 2022). "Recently, it was reported that CD4+ T cells become highly localized in the lung tissues post-infection with IBV." (PMID 35884922, 2022). "Cis-infection follows a productive infection in DCs, in which new viral progeny infects the CD4+ T cells through the classical CD4 receptor." (PMID 35802715, 2022). "Perivascular macrophages and microglia are the most commonly infected CNS resident cells, express low densities of CD4, and are exposed to an inflammatory environment at all stages of treated, and untreated, infection." (PMID 35975998, 2022). "One clinical study showed that zinc treatment reduced the infection incidence and increased CD4+ T cell counts and thymulin in HIV patients." (PMID 36290585, 2022). "In vitro infection of CD4 T cells shows that Th17 oriented cells account for 18% of the total population of infected cells and constitute a fifth of p24+ cells, whereas they represent only 6.2% of CD4 T cells." (PMID 35197986, 2022). "Peripheral CD4+ T-cell reduction in patients with TB has already been interpreted as a consequence of an augmented pooling of these cells at the site of infection." (PMID 36160177, 2022). "The immune system impairment has been previously reported in severe infection and neurodegenerative disease, both indicating the inverted ratio of CD4 T/CD8 T cells." (PMID 36846021, 2022). "CD40L−/− mice exhibited exacerbation of infection with a high fungal burden due to diminished interferon-γ production by CD4 and CD8 cells and decreased CD28 expression by CD4 cells." (PMID 35425769, 2022). "TMUV induces significant up-regulation of IL-2 and IFN-γ at 7 days post infection (pi), and significant increases in numbers of CD4+ and CD8+ T cells at 5 days pi." (PMID 36016955, 2022). "There was an inversion after the infection, and we observed that näive intrahepatic CD4+ and CD8+ T lymphocytes reduced drastically to less than 5%." (PMID 35720410, 2022). "During uroepithelial cell infection, CD4-PP significantly reduced uropathogen survival when treatment was given at the start of infection." (PMID 35821354, 2022). "We were interested in testing a model where induction of an inflammatory state would increase infection of cells in the CNS, possibly by inducing expression of the entry receptor CD4 or coreceptors CCR5 or CXCR4." (PMID 35975998, 2022). "In T. cruzi-resistant C57BL/6 mice, acute infection decreased CD4+ T cells in the spleen, while in BALB.xid and BALB/c mice, the acute infection increased CD4+ and CD8+ T cells in the spleen." (PMID 36107855, 2022).
infection (continued). "Of note, the same dynamic was observed in CD69 expressing CD4+ T cells, with a remarkable increase by day 4 post re-infection both in lung and airways." (PMID 35108347, 2022). "Infection was detected among 98/1463 (7%) of PWH with a CD4 count<500 cells/mm3 vs 152/2974 (5%) with counts ≥500 cells/mm3 (p=0.037), an association irrespective of SARS‐CoV‐2 serostatus." (PMID 35916394, 2022). "A single CD4+ T-cell count cannot provide reliable information on the length of infection for an individual since CD4+ T-cell counts are affected by many factors including sleep, exercise, diet and other infections." (PMID 34414881, 2021). "After correction, groups with low-level of CD3+, CD4+, and CD8+ T cells subsets showed a significantly increased risk of renal outcomes and infection." (PMID 34568395, 2021). "HHV-6 is able to induce immunomodulation via various mechanisms, such as lytic infection of CD4+ and/or cytotoxic effector T cells, the violation of antigen-representing functions, and inflammation induction." (PMID 34072365, 2021). "The immune effects of HIV at the time of untreated infection, indexed by nadir CD4 count, are related to brain function assessed by EEG even after many years of cART, and specific EEG measures in turn relate to current cognitive status." (PMID 34314416, 2021). "Strikingly, transcriptionally active CD4+ T cell infection (env+gag+) was observed in all acute infection CSF specimens surveyed." (PMID 34874976, 2021). "Focusing on outcomes, high-quality HIV care means that the patient seeks care early in infection (at a high CD4 count), starts ART quickly, is retained in care, and achieves immune recovery and viral suppression." (PMID 33789340, 2021). "The PBMCs from our LVLs were resistant to infection, but isolated CD4+ T-cells were capable of supporting low level viral replication." (PMID 34122382, 2021). "MCP-1 is a chemoattracting molecule of CD4+ T cells and monocytes whereas IL-8 predominantly attracts neutrophils, which are the first inflammatory cells to migrate to the infection site, restricting bacterial spread." (PMID 34456901, 2021). "Regarding the effect of the TMEV infection, the proportion of central and effector memory CD4+ T cells were decreased and augmented, respectively, in young mice, but not in old mice." (PMID 34355492, 2021). "During the infection, we observed that the number of effector CD4+ T cells presented a modest incremental trend in the spleen, reaching a 3.8-fold increase by day 28 post-infection." (PMID 34525131, 2021). "Over a period of years, the slowly amplifying cycle of virus infection, T cell death, and new infection results in a continued decline in CD4+ T cell numbers in the lymphoid tissues and peripheral circulation." (PMID 34696319, 2021). "As such, there are only few studies to date that have directly compared memory CD4+ T-cell responses, and in particular memory T-cell subsets following infection and vaccination." (PMID 34960185, 2021). "Infection by Brucella activates the participation of macrophages, dendritic cells, and CD4(+) and CD8(+) T cells." (PMID 33349157, 2021). "In order to provide more definitive evidence of a protective role for local CD4 T cells in clearance of a primary infection of B. pertussis, we used a CD4 T cell depletion approach, that depletes CD4 T cells from nasal tissue as well as the circulation." (PMID 33976385, 2021). "Due to the infection and subsequent depletion of CD4+ T cells and macrophages, HIV-1 exerts direct and indirect effects on the cellular immune pool." (PMID 34198973, 2021). "For instance, the airborne infection of mice, calves, and rhesus macaques with M. avium induced the activation of both CD4+ T cells and CD8+ T cells." (PMID 34835191, 2021). "We observed the same thing in vivo as our CD4+Trm were able to expand after a second infection with ΔPTX strain." (PMID 34564636, 2021).
infection (continued). "Our results suggest that conditions resulting in diminished cell-surface HA on fibroblasts, such as genital inflammation, can promote HIV transmission by conditioning CD4+ T cells toward a state more vulnerable to infection by HIV." (PMID 33976386, 2021). "Transcriptionally active or productive CD4+ T cell infection (env+gag+) was more limited and detected in CSF of two of twelve animals, those with the highest plasma viremia 4 weeks PI." (PMID 34874976, 2021). "Ils ont moins d'infections opportunistes 6 à 27%, des taux de CD4 plus élevés et des taux faibles d'antigène P24 dans le sang périphérique par rapport aux patients infectés sans DILS." (PMID 35686173, 2021). "We find that memory CD4 T cells generated by infection or immunisation survive secondary activation with antigen delivered without adjuvant, regardless of their location in secondary lymphoid organs or peripheral tissues." (PMID 32931017, 2021). "We found significantly more IFNγ and TNF producing CD4+ T cells in brains of infected TKO mice in the chronic stage of infection." (PMID 33968021, 2021). "Gp120 triggers WAVE2 phosphorylation through both CXCR4 and CCR5, acting through early Gαi independent and late Gαi dependent mechanisms, and inhibition of Arp2/3 activity significantly attenuated HIV-1 nuclear migration and infection of CD4 + T cells." (PMID 34429135, 2021). "In mild cases of infection, the CD4+ T cell response is recruited early during acute infection (>14 days), whilst the CD8+ T cell response lags behind and is recruited later." (PMID 35004764, 2021). "It is well known that HIV seeds into the gut within the first few weeks of infection and aggressively depletes memory CD4 T-cells in that tissue." (PMID 35058937, 2021). "It is known that precursor frequencies of rhinovirus-specific CD4+ T cells are very low, even during active infection (0.0004‒0.04% of CD4+ T cells)." (PMID 34350827, 2021). "In MDMs, M-tropic infection was enhanced by contact with infected CD4+ T cells, similar to previous literature." (PMID 33594125, 2021). "The severe infection itself also stimulated CD3Ɛ+CD4+CD25+Foxp3+ Tregs in the spleen cells from septic mice (CLP+PBS), but the increase of Tregs is more significant after treatment with Ts-AES." (PMID 33842398, 2021). "A CT3/4 associated antiviral state likely relates to recruitment of HIV target cells, CD4+CCR5+ T cells, to the FGT mucosa, increasing susceptibility to infection." (PMID 34604114, 2021). "The infection leads to the proliferation and differentiation of CD4+CD25+Foxp3+ Tregs via the activation of the TLR2 pathway." (PMID 34222495, 2021). "Another interesting characteristic of post-vaccination spike-specific CD4+ T cells from convalescent individuals relative to infection-naïve individuals was their expression of multiple tissue-homing receptors." (PMID 34636722, 2021). "In juvenile rabbits, an increase of MHC class II early after the infection with RHDV GI.1 was connected with an upregulation of CD4+ gene activity, and also with an increased survival rate in contrast to RHDV GI.2-infected rabbits." (PMID 33805607, 2021). "In dLNs, the frequency of Tregs within the CD4+ T cell compartment was rather stable upon infection, and only a mild drop was observed at 7 dpi, which rapidly returned to baseline levels already between 8 and 9 dpi." (PMID 34299148, 2021). "Unsurprisingly, there was a progressive loss in the CD4/CD8 ratio across the acute (P = 0.0156) and chronic (P = 0.0156) phases of infection." (PMID 34721397, 2021). "The median pre-infection CD4+ T cell counts in IR-infected animals was 1061/μL blood (range: 691 to 1673)." (PMID 33801437, 2021). "It is important to highlight that this study constitutes the first investigation that compares other CD4 profiles through a set of single-infection experiments with two T. cruzi strains that yield differential outcomes." (PMID 34712620, 2021).
infection (continued). "This study showed that RSA59 infection induces a significant upregulation of CD4+ T cell activation marker and costimulant for CD40 on microglia/macrophage, CD40L in WT mice." (PMID 34898656, 2021). "Depletion of CD4+ LTi cells led to a decline in the expression of infection-induced IL-22 and anti-microbial peptides that impaired innate immunity in the intestine." (PMID 34804991, 2021). "The protective effect was T cell-dependent, as depletion of CD4 or CD8 T cells immediately prior to challenge resulted in a substantially attenuated infection course." (PMID 34452460, 2021). "This led to a significant rise in the bacterial counts of ΔhisD 48 h post infection, reversing the effects of CD4 stimulation." (PMID 33767335, 2021). "Two weeks after infection, isolated lung leukocytes were analyzed by flow cytometry regarding the presence of CD4+ T cell subsets." (PMID 33936043, 2021). "A subject (RV001) was experimentally infected with rhinovirus (RV-A16) and CD4+ T cell signatures monitored by spectral flow cytometry in conjunction with tetramer staining during the course of infection." (PMID 34350827, 2021). "In contrast to central memory T-cells, the proportions of effector memory T-cells as a percentage of specific CD4+ T-cells were significantly lower, and the proportion of effector T-cells significantly were higher after infection than after vaccination." (PMID 34960185, 2021). "Decreased CD4+ naïve T cell count was independently associated with CVEs, whereas decreased CD8+ naïve T cell count was independently associated with infection episodes in HD patients." (PMID 33815398, 2021). "The levels of PD-1 were also shown to be high on exhausted CD4+ T cells during LCMV Cl 13 infection." (PMID 34696381, 2021). "We did observe waning of proliferative responses in youngsters in time, as frequencies of proliferated CD4+ T cells to Bp132 and PT S1 peptide pools were significantly lower in the late phase post infection compared to the early phase." (PMID 35822011, 2021). "Both Toxoplasma and microbiota specific CD4+ T cell populations underwent infection-induced expansion in the MyD88+/+ and MyD88-/- lamina propria." (PMID 34597344, 2021). "Needle challenge elicits similar early IFN-γ-producing CD4+ T cell responses at the site of secondary challenge when compared to Leishmania infected sand fly challenge, the natural mode of infection." (PMID 34543348, 2021). "The second Sp19F infection at day 7 elicited rapid recruitment of CD4+ cells on days 8–10 in the loose interstitium of the bronchovascular bundles, surrounding the coordinated arterial and airway branching trees of the lower respiratory tract." (PMID 34611166, 2021). "The risk of infection with HR HPV types and subsequent development of cervical abnormalities in WLWH correlates with HIV-1 viral load and low CD4 cell counts attributing HPV-related CC in WLWH to HIV-1 induced immune suppression." (PMID 34208764, 2021). "CD4+ T cells assist in fostering the development of cytotoxic memory CD8+ T cells following infection." (PMID 34445713, 2021). "Our previous studies showed that TH2 cells are the predominant CD4 T-cell subset during lethal infection and enhance disease progression." (PMID 35186781, 2021). "It is well established that activation of CD4+ T-cells enables their infection by HIV, and that the percentage of activated T-cells is increased in people with treated HIV infection." (PMID 34421607, 2021). "CD4+ T cells also drive the cytokine production that recruits other immune cells to the site of infection." (PMID 33998837, 2021). "At 7 days post-infection we observed a significant decrease in CD4+CD8+ double positive (DP) T-cells and NK T-cells (CD3+CD56+) within the bone marrow." (PMID 34106915, 2021). "All subsets except CD4+/CD25+ returned to (or were above) the preinfectional level by day 22 post infection." (PMID 34578316, 2021).